RNU6-806P (RNA, U6 small nuclear 806, pseudogene)
Gene: Small nuclear RNA gene on chromosome 5 (60,304,047 to 60,304,151, reverse strand). Ensembl gene ENSG00000202017.
Homologues: Orthologues: chimpanzee U6 (97% identical), macaque U6 (89% identical), rabbit U6 (73% identical), dog U6 (72% identical). Paralogues in human: RNU6-38P (88% identical), RNU6-20P (87% identical), RNU6-1145P (86% identical), RNU6-29P (86% identical), RNU6-39P (86% identical), RNU6-639P (86% identical), RNU6-1316P (85% identical), RNU6-16P (85% identical), RNU6-25P (85% identical), RNU6-476P (85% identical), RNU6-574P (85% identical), RNU6-1 (84% identical), and 1287 more.